GHRH (growth hormone releasing hormone)
Diseases named in the same sentence as GHRH in open-access papers (continued):
Sharing a sentence is not in itself a finding about the gene and the disease.
Alzheimer disease (5 papers, 2012 to 2026). A progressive, neurodegenerative disease characterized by loss of function and death of nerve cells in several areas of the brain leading to loss of cognitive function such as memory and language. "Synthetic GHRH antagonistic analogs can alleviate cognitive declines caused by acute exposure to toxicants or degenerative models of Alzheimer’s disease (AD)." (PMID 40943436, 2025). "The GHRH antagonist influenced the transcription of almost 2 dozen putative Alzheimer's disease markers according to the PCR Array experiments." (PMID 23211425, 2012). "Inhibition of the different levels of the GHRH-GH-IGF axis apparently exerts a beneficial impact on the progress of Alzheimer's disease." (PMID 23211425, 2012). "Our data strongly suggest the merit of further studies with GHRH analogs in models of Alzheimer's disease and in elementary clinical trials." (PMID 23211425, 2012). "In the in vivo studies, the GHRH antagonist significantly and dose-dependently delayed the Alzheimer's disease-related deterioration of the acquisition phase in MWM." (PMID 23211425, 2012). "Similarly, MIA-690, a GHRH antagonist, induced beneficial effects in different models of Alzheimer’s disease, showing anti-oxidative and neuro-protective effects." (PMID 37998350, 2023). "Taken together, our data suggest that further studies are needed to clarify the mechanism of action of GHRH analogs in models of Alzheimer's disease, with special emphasis on the separation between the acute effects on memory formation and the selective impact on proteo-toxicity itself." (PMID 23211425, 2012). "Changes in corticotrophin releasing hormone (CRH), luteinizing hormone-releasing hormone (LHRH), and GHRH secretion related to obesity, hyperinsulinemia and altered leptin signaling may play a role in the development of Alzheimer's disease." (PMID 23211425, 2012). "GHRH also increases the level of IGF-1, thereby collectively improving Alzheimer’s disease (AD)-and obstructive sleep apnea (OSA)-related cognitive dysfunction." (PMID 29273763, 2017). "Present experiments demonstrate that the GHRH antagonist, MIA-690, has several beneficial effects in each of the different models of Alzheimer's disease." (PMID 23211425, 2012). "Regarding the GHRH-GH-IGF axis, MIA-690 decreased the secretion of IGF-I in the supernatant of HCN-2 cell cultures which is critical since in Alzheimer's disease one of the most important pathologic phenomena, is the competition of insulin and amyloid-β for insulin-degrading enzyme (IDE)." (PMID 23211425, 2012). "The role of the GHRH - GH – IGF-I axis in the regulation of learning processes and the development of Alzheimer's disease, however, has not been completely clarified." (PMID 23211425, 2012).
gangliocytoma (5 papers, 2008 to 2025). A well differentiated, slow growing neuroepithelial neoplasm composed of neoplastic, mature ganglion cells. "Another rare situation is a hypothalamic GHRH-producing gangliocytoma that may stimulate somatotroph hyperplasia but more often co-exists with a sparsely granulated somatotroph PitNET." (PMID 34067494, 2021).
glioblastoma (5 papers, 2024 to 2025). The most malignant astrocytic tumor (WHO grade IV). "Antagonists of growth hormone-releasing hormone inhibit the growth of various experimental cancers including prostate, breast, ovarian, colorectal, lung, renal, endometrial cancers; glioblastomas and lymphomas." (PMID 38957466, 2024). "Interestingly, they found a negative correlation between the expression of GHRH and SV1 genes and the prognosis of glioblastoma; the higher expression correlates with poorer prognosis." (PMID 39934495, 2025).
hypothyroidism (5 papers, 2012 to 2022). Abnormally low levels of thyroid hormone. "In our case, PTH, TSH, and probably GHRH resistance were found at the same time, which induced electrolytes disturbance, hypothyroidism." (PMID 35600030, 2022). "In PHP-Ia/PHP-Ic, in addition to PTH resistance, hypothyroidism, growth hormone deficiency and hypogonadism are also demonstrable reflecting target-organ resistance to thyroid-stimulating hormone (TSH), growth hormone-releasing hormone (GHRH) and gonadotropins, respectively." (PMID 29280743, 2017). "Relatively less is known about thyroid regulation of the GHRH neurons, although hypothyroidism results in increased GHRH synthesis and release, and the severe growth retardation of the D3 KO mice suggests the importance of D3 in the regulation of the GHRH neurons." (PMID 22719854, 2012).
lung disease (5 papers, 2019 to 2025). "Functional findings implicate GHRH and GH in fibrosing lung disease, and they are consistent with demonstrated effects of the GHRH-R antagonist on mitochondrial respiration and fibroblast cytotoxicity." (PMID 31392398, 2019). "Overall, our results suggest that the development of GHRH antagonists may lead to new therapies against COVID-19 and related comorbidities, including lung diseases and sepsis-induced ARDS." (PMID 37649486, 2023). "Taken together, the novel data reviewed here show that GHRH is an important peptide that participates in lung homeostasis, inflammation, wound healing, and cancer; and GHRH-R antagonists may have therapeutic potential in lung diseases." (PMID 33096674, 2020).
melanoma (5 papers, 2013 to 2024). A malignant, usually aggressive tumor composed of atypical, neoplastic melanocytes. "The results showed that the expression of DSC3, DLL3, BMP6, SEMA4D, and GHRH are increased (p < 0.05) in melanoma, while the expression of LRRC4B, SFRP1, DCN, and CCL-8 decreased in melanoma (p < 0.05)." (PMID 36777724, 2023). "Then, we identified 9 LR pairs (“BMP6- > HJV” 、"CCL8- > ACKR4” 、"DLL3- > NOTCH3"、"DSC3- > DSG3"、"GHRH- > GHRHR” 、"LRRC4B- > PTPRF"、"SEMA4D- > PLXNB1"、"SFRP1- > FZD6"、"UCN- > CRHR1′′) as key LR pairs in melanoma prognosis through Lasso Cox regression and Multiple Stepwise Regression." (PMID 36777724, 2023). "GHRH can be found in melanoma, acting as an autocrine/paracrine growth factor." (PMID 36777724, 2023). "Moreover, primary human melanoma specimens were even found to have high levels of GH releasing hormone (GHRH) receptor (GHRHR), while GHRH-analogs were successful in suppressing malignant melanoma growth in vivo." (PMID 28223541, 2017). "Two DNA vaccines and therapies that were both released in 2007 must be especially emphasized: the canine melanoma vaccine and GHRH (growth hormone releasing hormone), which is applied in swine." (PMID 24983392, 2014).
myocardial infarction (5 papers, 2015 to 2026). Gross necrosis of the myocardium, as a result of interruption of the blood supply to the area, as in coronary thrombosis. "For cardiovascular indications, GHRH-R was recently found to be expressed by rat cardiomyocytes and administration of exogenous GHRH blocked apoptosis and reduced the cardiac scar size after myocardial infarction." (PMID 27774107, 2016). "We previously showed that growth hormone-releasing hormone (GHRH) agonists are cardioprotective following myocardial infarction (MI)." (PMID 25797248, 2015). "Thus, GHRH agonist, JI-38, has been shown to stimulate both cardiac myocyte and cardiac stem cell proliferation and survival in vitro; animals treated by GHRH agonists showed substantially improved cardiac performance and reduced infarct size after myocardial infarction." (PMID 27494841, 2016).
somatotropinomas (5 papers, 2014 to 2024). "After standardization, the effect of imatinib on somatotropinomas was compared with octreotide (0.1 μM), pasireotide (10 μM), and GHRH (0.5 μM)." (PMID 30210447, 2018). "The somatotropinoma cells were exposed to different concentration of GHRH (0–10 μM), octreotide (0–10−9 M) and pasireotide (0–20 μM)." (PMID 30210447, 2018). "Thus, increased GHRH expression has been found in aggressive somatotropinomas and pituitary hyperplasia have been observed in patients with endocrine carcinomas ectopically secreting GHRH." (PMID 25136513, 2014).
colon cancer (4 papers, 2000 to 2023). "To interfere with the production of IGFs, we treated male nude mice bearing xenografts of HT-29 human colon cancer with various potent growth hormone-releasing hormone (GH-RH) antagonists." (PMID 10817510, 2000). "Furthermore, the antagonization of GHRH has been shown to induce DNA damage in human colon cancer cells and subsequently to lead to p21-mediated cell cycle arrest and apoptosis." (PMID 36979698, 2023). "In keeping with these results, GHRH antagonists of JMR and MZ classes in combination with cytotoxic agents, including cisplatin and taxans, have been reported to inhibit the in vitro and in vivo growth of different experimental cancers, such as breast, lung and colon cancers." (PMID 36232554, 2022).
endometrial carcinoma (4 papers, 2014 to 2025). A malignant tumor arising from the epithelium that lines the cavity of the uterine body. "In the present study, we examined the effect of GHRH antagonist on the cell migration and invasion of two human endometrial cancer cell lines, Ishikawa and ECC-1, as well as the underlying molecular mechanisms of action involved." (PMID 28032599, 2017). "Our data demonstrate that targeting Twist and N-cadherin with a GHRH antagonist blocked Twist and N-cadherin-induced cell migration and invasion, specifying that the actions of a GHRH antagonist in endometrial cancer cells are highly associated with Twist and N-cadherin expression." (PMID 28032599, 2017). "However, to the best of our knowledge, the effect of GHRH on the invasion of human endometrial cancer cells remains unknown, and the underlying mechanisms by which GHRH regulates the endometrial cancer cell invasion need to be delineated." (PMID 28032599, 2017). "The aim of the present study was to investigate the expression of GHRH and its tumoral receptors and the presence of GHRH-R SVs in primary human endometrial carcinoma samples and in corresponding benign endometrial tissues." (PMID 35566020, 2022). "Our findings represent a new concept in the mechanism of GHRH antagonist-suppressed cell motility in endometrial cancer cells and suggest the possibility of exploring GHRH antagonists as potential therapeutics for the treatment of human endometrial cancer." (PMID 28032599, 2017). "Taken together, these results clearly indicated that GHRH antagonist exhibited an inhibitory effect on the cell migration and invasion in human endometrial cancer." (PMID 28032599, 2017). "In the present study, we demonstrated that a GHRH antagonist inhibited cell migration and invasion of endometrial cancer through the decreased the expression and Twist and N-cadherin." (PMID 28032599, 2017). "Here, we examined the effect of a GHRH antagonist on the motility of endometrial cancer cells and the mechanisms of action of the antagonist in endometrial cancer." (PMID 28032599, 2017). "Our study indicates that the GHRH antagonist inhibited the cell motility of endometrial cancer cells through the GHRH receptor via the suppression of Twist and N-cadherin." (PMID 28032599, 2017). "Our previous study has demonstrated that GHRH antagonist induces cell apoptosis in human endometrial cancer cells." (PMID 28032599, 2017). "Our previous study has demonstrated that GHRH and GHRH-R are expressed in human endometrial cancer cells." (PMID 28032599, 2017). "Our previous studies have demonstrated the direct antitumor effects of GHRH analogues in human endometrial cancer cells." (PMID 28032599, 2017). "The inhibitory effects of GHRH on human endometrial cancer cell migration and invasion were mediated by GHRH-R." (PMID 28032599, 2017). "Taken together, our data demonstrate that GHRH antagonist–inhibited invasion and migration of human endometrial cancer cells by down-regulating Twist and N-cadherin expression." (PMID 28032599, 2017). "GHRH antagonist suppresses the invasion and migration of endometrial cancer cells through binding of GHRH receptors and suppression of the Twist and N-cadherin pathways." (PMID 28032599, 2017). "GHRH and its receptor are also expressed in normal and tumorous endometrial tissue, and GHRH antagonists are promising chemotherapeutic agents for endometrial carcinoma." (PMID 25580121, 2014). "Ten of thirty-nine endometrial cancer specimens exhibited mRNA expression for GHRH but not for splice variants for GHRH-Rs." (PMID 35566020, 2022). "Moreover, immunohistochemical analyses showed that GHRH-R and GHRH are expressed in the tumor tissues of human endometrial cancer." (PMID 28032599, 2017). "In addition, the inhibitory effects of GHRH on human endometrial cancer cell migration and invasion were mediated by GHRH-R." (PMID 28032599, 2017).
endometrial carcinoma (continued). "Based on these studies, we hypothesized that GHRH antagonist inhibits human endometrial cancer cell migration and invasion by down-regulating the expression of N-cadherin." (PMID 28032599, 2017). "In conclusion, our results reveal that the potential role of a GHRH antagonist in inhibiting human endometrial cancer cell migration and invasion is through the binding of GHRH-R, and the subsequent down-regulation the expression of the metastasis-related proteins Twist and N-cadherin." (PMID 28032599, 2017). "Our data suggest that GHRH antagonist might be a potential molecule for the clinical treatment of human endometrial cancer." (PMID 28032599, 2017). "Based on the evidence that GHRH antagonists were able to suppress experimental tumor growth and that a subset of endometrial carcinoma expressed receptors for GHRH, the application of powerful new GHRH antagonists could be useful for the treatment of this type of malignancy." (PMID 39934495, 2025). "Therefore, GHRH antagonists have potent effects on endometrial tumors, suggesting that GHRH antagonists may be used as possible therapeutics for human endometrial cancers." (PMID 28032599, 2017). "Our findings provide new insights into the mechanism of GHRH antagonist-induced inhibition of cell migration and invasion in endometrial cancer and suggest the feasibility of developing GHRH antagonists as potential therapeutics for the clinical treatment of human endometrial cancer." (PMID 28032599, 2017). "Previous studies have shown that GHRH antagonists, such as MZ-J-7-118, MZ-5- 156 and JMR-132, inhibited the growth of human experimental endometrial carcinomas both in vitro and in vivo." (PMID 39934495, 2025). "Antagonists of growth hormone-releasing hormone (GHRH) inhibit the growth of various tumors, including endometrial carcinomas (EC)." (PMID 35566020, 2022). "In the present study, our results showed that both mRNA and protein levels of GHRH and GHRH-R SV1 were expressed in two human endometrial cancer cell lines, Ishikawa and ECC-1." (PMID 28032599, 2017). "In the present study, we demonstrated for the first time that a GHRH antagonist, MIA-602, inhibited the cell migration and invasion of human endometrial cancer by down-regulating Twist and N-cadherin expression." (PMID 28032599, 2017). "However, the mechanisms of the suppression of cell migration and invasion of GHRH antagonists, such as MIA-602, in endometrial cancer cells were unresolved until the present study was performed." (PMID 28032599, 2017).
hyperprolactinemia (4 papers, 2019 to 2024). Abnormally high level of prolactin in the blood. "Literature review of cases with hyperprolactinemia associated with ectopic acromegaly due to GHRH secretion." (PMID 39449742, 2024).
hypopituitarism (4 papers, 2010 to 2023). A condition of diminution or cessation of secretion of one or more hormones from the anterior pituitary gland. "Reduced levels of GHRH cause hypopituitarism, as also observed in for instance GHRH-/- and PC1/3-/- mice." (PMID 26275221, 2015). "Finally, our work confirms that the GH response to GHRH + ARG is significantly more compromised in patients with three or more pituitary hormone deficiencies than in patients without deficiencies." (PMID 37062055, 2023). "The GHRH + arginine test may give false normal results in patients with GHD secondary to hypothalamic damage, such as those with radiation induced hypopituitarism." (PMID 22899919, 2012).
lung carcinoids (4 papers, 2022 to 2024). "More rarely, an ectopic secretion of growth hormone-releasing hormone (GHRH) was reported, mainly sustained by pancreatic or pulmonary carcinoid tumors." (PMID 37373068, 2023). "Several hormones, including serotonin (84%), pancreatic polypeptide, gastrin, gastrin-releasing peptide, calcitonin, ACTH, and growth-hormone-releasing hormone often show positive immunostaining in lung carcinoids; multiple hormones may be found in the same tumor." (PMID 38001701, 2023).
ovarian carcinoma (4 papers, 2010 to 2024). A malignant neoplasm originating from the surface ovarian epithelium. "Surgical specimens of human prostate, breast, endometrial, and ovarian cancers were identified to contain GHRH mRNA, and a variety of human cancer lines and tumor samples express mRNAs encoding four possible splice variants (SVs) of GHRH-Rs with high-affinity binding sites for GHRH and its analogs." (PMID 39417961, 2024). "GHRH and GHRH-R are expressed in diverse tumor cells including human breast, endometrial, and ovarian cancers." (PMID 27774107, 2016). "Although these observations have demonstrated the inhibitory role of GHRH antagonists on the proliferation of ovarian cancer, the effects of GHRH antagonists on other aspects of cancer phenomena, such as apoptosis, is poorly understood." (PMID 20509930, 2010). "It was found that the treatment with the GHRH antagonists inhibit the growth of many human cancers, including ovarian cancer cell lines." (PMID 20509930, 2010). "The effect of the GHRH antagonist JMR-132 on ovarian cancer cells was primarily studied with the MTT assay." (PMID 20509930, 2010). "In summary, we show here for the first time that the GHRH antagonist JMR-132 acts as an effective anti-proliferation agent in the ovarian cancer cell lines, SKOV3 and CaOV3, by inducing apoptosis." (PMID 20509930, 2010). "The present study demonstrates that the inhibitory effect of the GHRH antagonist JMR-132 on proliferation is due, in part, to an interference with the EGFR-Akt pathway in ovarian cancer cells." (PMID 20509930, 2010). "However, the molecular mechanisms linking GHRH antagonists to the EGFR pathway in ovarian cancer cells were not well established." (PMID 20509930, 2010).
pancreatic cancer (4 papers, 2016 to 2025). "The 44-amino acid forms of GHRH were first isolated and identified from human pancreatic tumors and only subsequently purified from hypothalamic tissue." (PMID 39934495, 2025). "GHRH (NH2 1–29) peptide antagonists inhibit the growth of prostate, breast, ovarian, renal, gastric, pancreatic cancer in vitro and in vivo." (PMID 35061691, 2022).
Pancreatic NET (4 papers, 2016 to 2026). "We report a case of a female patient who presented with primary hyperparathyroidism (pHPT) and a GHRH- and insulin cosecreting pancreatic NET (pNET) and genetically confirmed multiple endocrine neoplasia type 1 (MEN1), within an undiagnosed family with various MEN1-related NETs." (PMID 42007244, 2026).